OR5BS1 (olfactory receptor family 5 subfamily BS member 1)
Description:
Odorant receptor.
Synonyms: OR5BS1P
Gene: Protein-coding gene on chromosome 12 (48,559,882 to 48,562,956, forward strand). Ensembl gene ENSG00000198678.
Subcellular location: Cell membrane
Gene Ontology:
Molecular function: odorant binding; olfactory receptor activity; G protein-coupled receptor activity
Biological process: sensory perception of smell; detection of chemical stimulus involved in sensory perception of smell; G protein-coupled receptor signaling pathway
Cellular component: plasma membrane; membrane
Homologues: Orthologues: macaque OR5BS1P (93% identical), dog OR5BS1 (80% identical), mouse Or5bs2 (77% identical), rat Or5bs2 (76% identical). Paralogues in human: OR8S1 (50% identical), OR7C2 (46% identical), OR7C1 (45% identical), OR2A5 (45% identical), OR7D2 (44% identical), OR2A1 (44% identical), OR2A42 (44% identical), OR1F1 (44% identical), OR7A17 (44% identical), OR7D4 (43% identical), OR1S1 (43% identical), OR7A5 (43% identical), and 116 more.